MIR3614 (microRNA 3614)
Synonyms: hsa-mir-3614; mir-3614
Gene: MicroRNA gene on chromosome 17 (56,891,270 to 56,891,355, reverse strand). Ensembl gene ENSG00000284542.
Homologues: Orthologues: chimpanzee MIR3614 (100% identical).
Diseases named in the same sentence as MIR3614 in open-access papers:
MIR3614 is named in the same sentence as 4 diseases in open-access papers, as found by Europe PMC text mining. Sharing a sentence is not in itself a finding about the gene and the disease.
MIR3614 shares sentences with these, for which no sentence is quoted: atypical hemolytic-uremic syndrome (1 paper); microangiopathic hemolytic anemia (1); renal failure (1); Thrombocytopenia (1).